KRAS (KRas proto-oncogene, GTPase)
Diseases named in the same sentence as KRAS in open-access papers (continued):
Sharing a sentence is not in itself a finding about the gene and the disease.
melanoma (continued). "The mutation frequency of KRAS was also significantly enriched relative to the frequency of extracranial melanoma metastases; 8% (4/50) in our dataset vs 2.1% (6/274) in extracranial melanoma metastases in SKCM-TCGA (p = 0.0413, logistic regression Wald t test)." (PMID 33024263, 2021). "There is another approach of ACT by identifying RAS‐mutant specific antigens for the treatment of NRASmut melanoma and have some breakthroughs in the treatment of NSCLC with KRAS mutation." (PMID 41492362, 2026). "This is consistent with published data showing that preclinically the combination of type II RAF inhibitors and MEK inhibitors is synergistic in colorectal, melanoma, and lung tumor cell lines with mutations in NF1, BRAF, or KRAS." (PMID 40111124, 2025). "Genetic mutations in KRAS, NRAS, and BRAF were commonly implicated in the development of both melanoma and CRC, while mutations in CDKN2A and BRCA2 were specifically significant in melanoma." (PMID 40447784, 2025). "This study highlights the importance of KRAS signaling and macrophage infiltration in melanoma prognosis." (PMID 40607411, 2025). "The multifaceted investigation integrating KRAS pathway perturbations, macrophage-related gene expression, and immune landscape analyses has culminated in a more comprehensive understanding of melanoma’s complex biology." (PMID 40607411, 2025). "Like KRAS mutations, BRAF can be present in both cancers but appears to be more prevalent in melanoma development than in CRC development." (PMID 40447784, 2025). "Combination regimens involving OV and ICIs demonstrated enhanced ORRs, particularly in melanoma and KRAS-mutant NSCLC, suggesting synergistic effects." (PMID 41150456, 2025). "Beyond its direct influence on tumor cells, KRAS signaling appears to shape the immunological landscape of melanoma through an intricate web of cytokines, chemokines, and other regulatory factors." (PMID 40607411, 2025). "The capacity of the KRAS-Macrophage Prognostic Associated Gene (KMPAG) signature to delineate high-risk and low-risk melanoma cohorts underscores its translational potential for refining clinical decision-making." (PMID 40607411, 2025). "Nevertheless, a subgroup of melanomas appears to exhibit activation of the KRAS pathway or dysregulation of key components therein." (PMID 40607411, 2025). "Genetic mutations in KRAS, NRAS, and BRAF were frequently observed in both melanoma and CRC, whereas BRCA2 and CDKN2A mutations were specific to melanoma." (PMID 40447784, 2025). "In the literature, both KRAS and HRAS mutations have been reported in approximately ~2% of melanomas." (PMID 41142596, 2025). "In contrast to KRAS mutations which are most frequently in codon 12, the most common NRAS mutations in melanomas occur at codon 61 (Q61R or Q61K)." (PMID 39379700, 2024). "Activating mutations in either of the three RAS isoforms (HRAS, KRAS, or NRAS) are found in nearly 20% of all human tumors with NRAS mutated in ~25% of melanomas." (PMID 39379700, 2024). "Of all RAS isoforms (HRAS, KRAS, and NRAS in humans), the most common mutation in melanomas occurs in the NRAS gene, while in other types of human cancers, mutations are more frequent in the KRAS gene." (PMID 39770908, 2024). "In fact, all genetic mouse models describing tumor suppressive activity of AMBRA1 so far have been generated on a mutated KRAS/BRAF/MAPK signaling background, and mutations of the KRAS/BRAF/MAPK pathway are common in DLBCL, LUAD, and melanoma." (PMID 39617889, 2024). "In the cBioPortal database, we found a frequency of 0.5–1.2% samples with CRKL and MAPK1 co-amplification with a trend to mutual exclusivity with KRAS, NRAS and BRAF mutations in NSCLC and melanoma." (PMID 37443114, 2023).
melanoma (continued). "KRAS mutations were more prevalent in NSCLC (p<0.01) and NRAS mutations in thyroid and melanoma (both p<0.05)." (PMID 37503077, 2023). "In our study, we also showed that additional mutations in genes such as KRAS and NEK10 were likely to be seen in primary melanoma." (PMID 38003476, 2023). "As the mitogen-activated protein kinase (BRAF-MAPK) signaling pathway is frequently activated in melanoma, we analyzed TERT in melanoma subtypes with hotspot mutations in BRAF, RAS (NRAS, KRAS, HRAS) and NF1 genes in the SKCM cohort." (PMID 37418389, 2023). "Four MEK inhibitors are meanwhile FDA approved to treat melanoma, neurofibroma, NSCLC and thyroid cancer in stratified patients with BRAF or KRAS mutations." (PMID 36675180, 2023). "The prevalence of co-altered mutations in the MAPK pathway in melanomas was the highest among the cancer types we analyzed and was 61.1% for HRAS, 59.4% for KRAS, and 31.3% for NRAS-mutant tumors." (PMID 37503077, 2023). "For instance, pan-RAF inhibitor LXH254 blocks dimeric BRAF and CRAF, which can provide a potential clinical strategy when combined with MEK or ERK inhibitors to treat KRAS mutant NSCLC or NRAS mutant melanoma." (PMID 38111008, 2023). "This study employed the CRISPR/Cas9 technology to generate three isogenic A375 melanoma cell lines with point mutations of NRAS Q61K, KRAS G13D and MEK1 Q56P, respectively." (PMID 36358868, 2022). "Mutations in other genes of the same RAS family, such as HRAS or KRAS, are uncommon in CM, although they have also been identified in other melanoma subtypes (acral, mucosal, Spitz)." (PMID 36143375, 2022). "Regarding EGFR-mediated control of tensile Rac1 activity, ERK/MAPK signalling has been implicated to drive the overexpression and activation of the Rac-GEF in BRAF- and NRAS-mutant melanoma, as well as in KRAS- and EGFR- mutant lung cancer." (PMID 36224221, 2022). "We employed CRISPR/Cas9 genome engineering to introduce NRAS Q61K, KRAS G13D and MEK1 Q56P mutations into the A375 melanoma cell line with endogenously high expression of BRAF V600E." (PMID 36358868, 2022). "Given the rapidly evolving combination treatment landscape, future studies using the KRAS G13D/BRAF V600E isogenic model of drug-resistant melanoma described here should focus on combination PD-L1 and BRAF/MEK inhibitor treatment." (PMID 36358868, 2022). "A large-scale study conducted by our group previously reported similar cytotoxic effects to other tumor types, such as melanoma, pancreas esophagus cell lines, where the majority (70%) of the KRAS mutant cell lines were classified as allitinib resistant." (PMID 35887120, 2022). "Inactivation of NF1 increases HRAS, KRAS, and CRAF activities in mutated melanoma cells (BRAFV600E), restoring ERK activation even in the presence of BRAFi." (PMID 36286442, 2022). "RAS family members KRAS and NRAS are frequently mutated in colorectal and pancreas adenocarcinoma, and multiple myeloma and melanoma, respectively." (PMID 35768873, 2022).
melanoma (continued). "Higher levels of YAP were detected in the majority of NSCLC and melanoma tumors harboring BRAF V600E and NSCLC tumors with KRAS mutations, compared to tumors expressing wild-type BRAF and KRAS." (PMID 33467099, 2021). "Among RAS isoforms, KRAS mutations are most frequently found in pancreatic, colorectal and lung adenocarcinomas, while NRAS and HRAS are generally mutated in some melanomas, leukemias and thyroid cancers." (PMID 34946644, 2021). "Consistent with NSCLC patient data sets, almost half of melanoma patients possess activating mutations in the MAPK pathway, including KRAS and BRAF." (PMID 33972557, 2021). "The cBio Cancer Genomics Portal (cBioPortal) is one of the most comprehensive public databases and allowed us to analyze the BRAF, KRAS, and KIT mutation status from 14 different studies focused on melanomas." (PMID 34769348, 2021). "While KRAS mutations are more prevalent in adenocarcinoma, NRAS mutations are more prevalent in melanomas, thyroid cancers, and leukemias." (PMID 34830283, 2021). "In summary, our analyses indicate that the patterns of melanoma recurrence may be at least partially determined by the tumour mutational profile and that up to 8% of patients developing early brain metastases may have tumours driven by oncogenic KRAS mutations." (PMID 33024263, 2021). "Mutations in KRAS and HRAS occur at a low frequency in melanomas, occurring at 1.7% and 1.9%, respectively." (PMID 34831002, 2021). "Oncogenic mutations in RAS genes (KRAS, NRAS, and HRAS) or RAF genes (RAF-1, BRAF, and A-RAF) occur in many cancer types, including the melanoma cells." (PMID 34822435, 2021). "KRAS was the most frequently mutated of the three in adenocarcinoma, and NRAS was the most frequently mutated in melanoma." (PMID 34645806, 2021). "This is further confirmed by the analysis of YAP levels in human tumor specimens collected from patients with NSCLC and melanoma encoding BRAF V600E mutations, NSCLC patients with KRAS mutations, and NSCLC patients with wild-type BRAF and KRAS." (PMID 33467099, 2021). "There has been a great deal of progress in targeting downstream effector proteins of KRAS for the treatment of melanoma." (PMID 33801965, 2021). "Further, only 1.6% (3/186) of melanoma cases in the Memorial Sloan Kettering MSK-IMPACT dataset were KRAS mutant, significantly lower than in our early brain metastasis discovery cohort (p = 0.0327, logistic regression Wald t test)." (PMID 33024263, 2021). "EGFR-directed treatment strategies were introduced in colorectal adenocarcinomas wild-type for NRAS and KRAS and BRAF inhibitor treatment finds application in BRAF V600E mutated malignant melanomas." (PMID 33227073, 2020). "Like in melanoma, miR-622 expression was strongly downregulated and inversely correlated with KRAS expression in human HCC tissues." (PMID 31906510, 2020). "KRAS mediated the effects of a loss of this miRNA both in HCC and in melanoma and we demonstrated strong anti-tumor effects of the novel small molecule inhibitor of KRAS, deltarasin, in HCC and melanoma in vitro and in vivo." (PMID 31906510, 2020). "For example, 90% of KRAS mutations in pancreatic ductal adenocarcinoma are at the position G12, while 90% of NRAS mutations in melanoma are at Q61." (PMID 31941155, 2020). "Considering that this hotspot of KRAS has more clinical significance than that of the rare mutation in BRAF based on the knowledge at present, this melanoma was classed into the RAS group." (PMID 32083130, 2020). "For trametinib, PC2 identified a pattern of differential response among trametinib-sensitive cell lines, distinguishing the responses of mostly BRAF mutant melanoma lines from other sensitive lines (largely KRAS mutant)." (PMID 32855387, 2020).
melanoma (continued). "We focused our attention on the EGFR gene for NSCLC samples, KRAS, and BRAF genes for mCRC samples, and the BRAF gene for melanoma samples, because target therapy for the mutation of these genes can be prescribed by clinicians." (PMID 32054005, 2020). "To highlight the utility of our platform, we generated substitution mutations in each exon of three human genes (MAP2K1, KRAS, NRAS) associated with resistance to vemurafenib, which is a cancer drug targeting the BRAF V600E mutation in melanoma patients." (PMID 32242071, 2020). "Recently, RASA2 and NRAS mutations were confirmed to be mutually exclusive, with NF1 mutations significantly co-occurring with RASA2 mutations in BRAF and NRAS wild-type melanomas, since RASA2 inhibits NRAS and NF1 inhibits KRAS and HRAS." (PMID 32850962, 2020). "Recently, we identified wildtype KRAS as a novel therapeutic target in melanoma and showed that KRAS inhibition functions synergistically with BRAF inhibition." (PMID 31906510, 2020). "There is also strong tissue predilection of the occurrence of RAS isoform mutations; while KRAS monopolizes pancreatic cancers, NRAS mutants dominate melanoma and AML." (PMID 31941155, 2020). "In a genetically engineered mouse model, conditional melanocyte-specific expression of either BRAF D594A or KRAS G12D was insufficient to induce nevi or melanomas." (PMID 31398831, 2019). "In particular, in this study we retrospectively analysed advanced melanomas that had directly progressed from stage IB/II AJCC (American Joint Committee on Cancer) 2017, whose mutational status of BRAF, KRAS, NRAS and PIK3CA genes had already been tested." (PMID 30934988, 2019). "Prior to the cessation of pembrolizumab corresponding to the melanoma complete response, KRAS mutant ctDNA levels was at its peak (14 c/mL)." (PMID 31727009, 2019). "A recent study has reported that miR-326 serves as a tumour suppressor in melanoma by targeting KRAS and regulating the AKT and ERK signalling pathways." (PMID 31273188, 2019). "We propose a restricted panel for BRAF, KRAS/NRAS, KIT, CCDN1, and CDK4 mutations in the routine diagnostic test in order to better classify the SNM subtypes of melanoma." (PMID 31581559, 2019). "Among the five melanomas harboring a rare BRAF mutation, two samples with the BRAF p.Asp594Asn showed an additional mutation in the NRAS (p.Gly12Asp) or in the KRAS (p.Gln61His) gene, previously identified in routine analysis." (PMID 31547467, 2019). "In a panel of 49 melanoma-derived cell lines, we sequenced oncogenes that are commonly mutated in melanoma (BRAF, NRAS, KRAS)." (PMID 31253656, 2019). "LY3009120 inhibited the proliferation of melanoma cells with either BRAF or NRAS and colorectal cancer cells with BRAF and KRAS mutations by inducing G0/G1 cell cycle arrest." (PMID 29455659, 2018). "SK-Mel-2 melanoma cells have been reported to contain either an NRASQ61R or a KRASQ61R mutation, but sequencing of the amplified exons 3 of NRAS and KRAS in the cells used in our experiments confirmed that the mutation is NRASQ61R, not KRASQ61R." (PMID 29481571, 2018). "MLPA was conducted to detect chromosomal alterations and Sanger sequencing used to identify point mutations in candidate melanoma driver genes (BRAF, NRAS, KRAS, GNA11, GNAQ), and other genes implicated in melanoma prognosis (EIF1AX, SF3B1)." (PMID 30558566, 2018). "Specifically, we pursued supervised analyses of genetic networks by stratifying melanoma cell lines into groups defined by BRAF and/or KRAS mutation status and then evaluating differences in the overall network structure (i.e., relationships between genes)." (PMID 30042785, 2018). "For the TGen melanoma cell lines, WGCNA modules were created using BRAF and KRAS mutation groupings." (PMID 30042785, 2018). "In this study, we examined POM for alterations in candidate melanoma driver genes (BRAF, NRAS, KRAS, GNA11, GNAQ) and genes implicated in UM prognosis (EIF1AX, SF3B1, BAP1)." (PMID 30558566, 2018).
melanoma (continued). "Treatment of BRAFV600E melanomas invokes resistance in BRAFV600E melanoma cells, with mechanisms of resistance including the development of upstream mutations in NRAS or KRAS." (PMID 29481571, 2018). "We then tested these intersecting genes for network rewiring using network equivalence and permutation tests (although we were unable to test for KRAS because of the limited number of KRAS+ melanoma cell lines)." (PMID 30042785, 2018). "RAS activating mutations occur in 30 % of all cancers, including a high prevalence in melanoma (15–25 %), with KRAS mutations more common in adenocarcinomas and solid tumors and NRAS mutations more common in leukemia, thyroid carcinoma, and malignant melanoma." (PMID 27650277, 2017). "Twelve out of 71 (16.9%) mucosal melanomas analyzed harbored RAS mutations, 8 in the NRAS and 4 in the KRAS gene." (PMID 28380455, 2017). "An increasing number of studies also indicate that KRAS mutations (G12C or G12D) are required for BCC, SCC and melanoma development." (PMID 27901498, 2017). "In keeping with published studies, there were frequent mutations of BRAF and NRAS in melanoma; BRAF, EGFR, KRAS, and STK11 in NSCLC; APC, BRAF, KRAS, and PIK3CA in CRC; KIT and PDGFR3A in GIST; and CTNNB1 in other tumours (desmoid fibromatosis)." (PMID 28196074, 2017). "For example, mutations in KRAS are common in lung, colon, and pancreatic cancers, those in NRAS predominate in melanoma, and HRAS mutations are commonly seen in bladder, head and neck, and skin cancers." (PMID 29349077, 2017). "Mutations in HRAS are most frequently found in melanoma, bladder and mammary carcinoma; NRAS mutations are found in melanoma and thyroid carcinoma; and KRAS mutations are most prevalent in cancers of the bladder, ovary, thyroid, lung, colon and pancreas." (PMID 27096871, 2016). "KRAS amplification was also observed in a tumor at recurrence in a melanoma patient treated with combination BRAF and MEK inhibitor therapy." (PMID 27081080, 2016). "In general, mutations in position 16 and 102 can be seen as a signature of two types of cancer: colorectal, characterized by KRAS G12, and melanoma, characterized by NRAS Q61." (PMID 26860319, 2016). "In melanomas, the MAPK pathway is frequently hyperactivated by mutations in the BRAF gene (approximately 50% of melanomas) but also in NRAS (18%), KIT (9%), HRAS (2%) or KRAS (2%) genes (COSMIC database)." (PMID 26098773, 2015). "In LN, MAPK3 (cf = 53), PIK3R1 (cf = 51), HRAS (cf = 46), PIK3R2 (cf = 45) and KRAS (cf = 44) are the top 5 cross-talk genes, and as expected most of these are already recognized melanoma markers." (PMID 26558755, 2015). "The frequency of concomitant KRAS or NRAS mutations found in a BRAF-mutated tumor was 4 of 33 (12 %) in NSCLCs, 3 of 34 (8.8 %) in CRCs, or 3 of 67 (4.5 %) in melanomas." (PMID 26498038, 2015). "To validate the NGS platform we first analyzed seven independent tumor FFPE samples from lung, colon and melanoma with known mutations in BRAF (V600E), KRAS (G12S, G13D), and EGFR (L858R and E746_A750del)." (PMID 26124082, 2015). "We therefore examined the impact of PLX4032 and MEKi on RHOB expression in wild type BRAF melanoma cells harboring mutations in NRAS (WM1346 and SK-MEL2 cells), KIT (WM3211 cells) or KRAS (WM1791C cells)." (PMID 26098773, 2015). "Although cancers like melanoma or pancreatic adenocarcinoma are driven by point mutation of oncogenes BRAF and KRAS, respectively, EAC appears to obtain its oncogenic drive through amplification." (PMID 25351503, 2014). "There were three indeterminate calls (one melanoma-2 and two with thyroid-1) for the KRAS portion of the assay." (PMID 23991070, 2013). "A recent study suggests that overexpression of PDE4 enzymes is critical for the MAPK activation by oncogenic-RAS in melanoma cells, indicating the novel strategy targeting PDE4 activity in melanoma cells with oncogenic KRAS." (PMID 22830422, 2012).